Y_RNA (Y RNA )
Gene: Miscellaneous RNA gene on chromosome 1 (93,385,711 to 93,385,817, forward strand). Ensembl gene ENSG00000207379.
Homologues: Orthologues: chimpanzee Y_RNA (99% identical), macaque Y_RNA (95% identical). Paralogues in human: RNY1P5 (89% identical), Y_RNA (89% identical), Y_RNA (88% identical), Y_RNA (87% identical), Y_RNA (86% identical), RNY1P2 (85% identical), Y_RNA (85% identical), Y_RNA (84% identical), RNY1 (83% identical), RNY1P6 (83% identical), Y_RNA (83% identical), Y_RNA (82% identical), and 95 more.